REN (renin)
Diseases named in the same sentence as REN in open-access papers (continued):
Sharing a sentence is not in itself a finding about the gene and the disease.
Hyperkalemia (continued). "With an elevated ACTH with or without hyponatremia and hyperkalemia indicative of primary adrenal insufficiency, additional workup should include an abdominal CT, plasma renin, and 21-hydroxylase antibody serology while administering empiric treatment." (PMID 34660286, 2021). "However, if hyponatremia, hyperkalemia, and elevated plasma ACTH and renin levels in the setting of very low morning serum cortisol levels are found, primary AI is likely." (PMID 34268454, 2021). "The clinical trial involving aliskiren, a renin inhibitor, was stopped prematurely due to adverse events (hyperkalemia, hypotension, and cardiac arrest) and due to lack of benefit when compared to placebo." (PMID 28058051, 2016). "The presence of high plasma renin activity, aldosterone, and cortisol, along with the presence of hyponatremia and hyperkalemia, established the diagnosis of PHA type 1 and ruled out CAH." (PMID 26904317, 2016). "CACNA1HM1549V shows constitutive activity at membrane potentials close to the resting potential, allowing channels to be activated despite suppression of the renin-angiotensin system and absence of hyperkalemia." (PMID 25907736, 2015). "A systematic review and meta-analysis found that compared with the renin–angiotensin–aldosterone system inhibitor, patients treated with ARNI had lower incidence of composite renal impairment, ESRD, drug discontinuation due to renal events, severe hyperkalemia and a slower eGFR decline." (PMID 37430227, 2023). "SZC-incorporated up-titration of renin-angiotensin system inhibitors and mineralocorticoid receptor antagonists has been recommended for those with systolic heart failure, whereas SZC is often terminated following the improvement of hyperkalemia in real-world practice." (PMID 36142977, 2022). "Unfortunately, a large proportion of the reported cases failed to provide the level of ACTH and renin or whether there was hyperkalaemia, which might result in an overestimated incidence of ICI-PAI." (PMID 35870109, 2022). "The results suggest that, for 1000 UTIs treated with antibiotics among people 65 and over, treatment with trimethoprim instead of amoxicillin would result in one to two additional cases of hyperkalaemia and two admissions with acute kidney injury, regardless of renin-angiotensin system blockade." (PMID 29438980, 2018). "Our results show that trimethoprim is associated with greater risk of acute kidney injury and hyperkalaemia compared with other antibiotic drugs for a UTI, among the general population aged 65 and over, and not just those treated with renin-angiotensin system blockers." (PMID 29438980, 2018). "Indeed, the volume overload encountered during renal dysfunction stimulates the secretion of atrial natriuretic peptide (ANP), which has a negative effect on both renin and aldosterone secretion induced by hyperkalemia - resulting in hyporeninism - hypoaldosteronism." (PMID 38434606, 2024). "As with hyperkalemia, no established PAC thresholds exist for hyperreninemia, and unlike the former, there are no prior physiological studies from which expected aldosterone responses to high renin can be derived." (PMID 41517465, 2025).
atherosclerosis (173 papers, 2009 to 2026). A disease characterized by the build-up of fatty material and calcium deposition in the arterial wall resulting in partial or complete occlusion of the arterial lumen. "Multiple risk factors contribute to atherosclerosis development, which leads to the release of renin and aldosterone, causing resistant/malignant hypertension." (PMID 34094725, 2021). "Pathways linked to cell adhesion and renin-angiotensin signaling are also enriched – both pathways and processes that are known to be altered in vasculature in the setting of atherosclerosis and T2D." (PMID 33629656, 2021). "Elevated blood pressure can cause endothelial damage and atherosclerosis by increasing shear stress, enhancing the vascular tone, and activating the sympathetic nervous system and renin-angiotensin aldosterone system." (PMID 30646893, 2019). "The pattern of renin associations with measures of atherosclerosis burden, arterial stiffness and endothelial function were also similar in T2D subjects with or without treatment with RAAS inhibitors." (PMID 27596252, 2016). "Renin levels were significantly associated with the severity of atherosclerosis both in peripheral arteries and in the carotids." (PMID 27596252, 2016). "In this study, we report an unexpected increase in atherosclerosis progression with renin inhibition in high-risk patients who have established cardiovascular disease and receive aliskiren." (PMID 23686372, 2013). "The renin-angiotensin system increases blood pressure and has been linked to atherosclerosis." (PMID 40175777, 2025). "Atherosclerosis can begin with oxidative stress caused by the renin–angiotensin system (RAS), which could damage the blood vessel lining and causes endothelial dysfunction." (PMID 39199169, 2024). "This loss of β-cell function might result in higher SBP and LDL-C concentrations due to increased oxidative stress and activation of renin-angiotensin system, which would accelerate atherosclerosis and increase the risk of premature CVD." (PMID 36352412, 2022). "Inversely, poor BP control may initiate secondary mechanisms (e.g., the renin-angiotensin system and endothelial and vascular smooth muscle–related mechanisms), causing aggravated BP levels, atherosclerosis, and finally, target organ damage." (PMID 36568541, 2022). "Growing evidence has shown that vitamin D has an extensive noncalcemic pleiotropic function mediated by vitamin D receptor (VDR), associated with suppression of the renin-angiotensin system, anti-myocyte hypertrophy, atherosclerosis lowering and anti-inflammation." (PMID 35311238, 2022). "According to the literature, cold air can indirectly lead to an increase in cardiovascular risks through its effect on the sympathetic and renin-angiotensin systems, blood pressure, and risk factors for atherosclerosis, such as blood viscosity, the amount of fibrinogen, lipids and uric acid." (PMID 35011601, 2021). "Chronic hyperuricemia would stimulate the renin-angiotensin system and inhibit release of endothelial nitric oxide, contributing to vasoconstriction and atherosclerosis, then possibly increase blood pressure and cause renal and cardiovascular disease for the elderly." (PMID 28978911, 2017). "Previous studies have supported that vitamin D may reduce the risk of CVD by blocking the renin-angiotensin system, decreasing the parathyroid hormone levels, reducing inflammation, lowering coagulation, subsequently reducing atherosclerosis, and increasing insulin production." (PMID 39194949, 2024). "Additionally, cold air can indirectly lead to an increase in cardiovascular risks through its effect on the sympathetic and renin-angiotensin systems, blood pressure, and risk factors for atherosclerosis, such as blood viscosity and the amount of fibrinogen, lipids, and uric acid." (PMID 33381524, 2020).
atherosclerosis (continued). "It has been reported that vitamin D may influence blood pressure through the renin-angiotensin system, and a number of possible pathophysiological links to atherosclerosis have been ascribed to vitamin D deficiency, including activation of the renin angiotensin system." (PMID 22815708, 2012). "KEGG analysis identified pathways including AGE–RAGE signaling in diabetic complications, fluid shear stress and atherosclerosis, lipid and atherosclerosis, and renin–angiotensin system." (PMID 41226767, 2025). "Atherosclerosis and aortic stenosis almost always coexist in clinical practice; therefore, the three groups of drugs- statins, inhibitors of the renin-angiotensin axis, and PCSK9 inhibitors–deserve their place and indication in patients with aortic stenosis." (PMID 40870420, 2025). "And the renin-angiotensin system plays a crucial role in accelerating atherosclerosis, with reports indicating that T3 increases renin production and secretion." (PMID 41451128, 2025). "Local vitamin D activation by the VDR has various potential cardiovascular benefits including reduced renin production, relaxation of vascular smooth muscle cells, and reduced output of atherosclerosis-forming foam cells." (PMID 39194949, 2024). "Established therapies to treat oxidative stress-mediated atherosclerosis are statins, renin–angiotensin system inhibitors, and aspirin." (PMID 39199169, 2024). "Although this is the first report of PVAT involvement in atherosclerosis secondary to CKD+PD, Kawahito64 and colleagues previously showed that PVAT contributes to atherosclerosis in uninephrectomized ApoE−/− mice by activation of the renin‐angiotensin system." (PMID 38979792, 2024). "Compared to losartan, GalNAc AGT ASO led to more profound increases in plasma renin and reduction in BP but had similar effects on atherosclerosis." (PMID 37293374, 2023). "Further, inhibition of megalin, an endocytic receptor for many molecules including AGT and renin on renal proximal tubules, results in profound reductions of renal AngII concentrations and atherosclerosis." (PMID 37655218, 2023). "In summary, losartan leads to different magnitude of responsiveness on plasma renin concentrations and blood pressure between male and female mice, but comparable reductions in atherosclerosis in both sexes." (PMID 37655218, 2023). "Whole body manipulation of the renin-angiotensin system (RAS) consistently exerts profound effects on experimental atherosclerosis development." (PMID 37655218, 2023). "Many distinctive pathways associated with myocardial ischaemic pathophysiology were detected, such as Fibrosis, Atherosclerosis and Renin-angiotensin signalling both on d7 and 28 post-surgery." (PMID 36813782, 2023). "First, pharmacological inhibition of AT1R by losartan attenuates atherosclerosis in both male and female mice equivalently, although losartan suppresses blood pressure and increases plasma renin concentrations more profoundly in female mice." (PMID 37655218, 2023). "Promising drugs against AngII-induced atherosclerosis influence both pharmacological inhibitions of the renin-angiotensin system and the pro-oxidant properties." (PMID 36009011, 2022). "It was concluded that the 22 active ingredients acted on 176 targets by relevant pathways in lipid and atherosclerosis, renin–angiotensin system, HIF-1 signaling pathway, and so on." (PMID 35873580, 2022). "The most enriched pathways were renin secretion, renin-angiotensin system, hypertrophic cardiomyopathy, fluid shear stress and atherosclerosis, and adrenergic signaling in cardiomyocytes." (PMID 35498046, 2022). "Four significantly different pathways, VEGF signaling pathway, prolactin signaling pathway, renin-angiotensin system, and fluid shear stress and atherosclerosis, included 49 DEPs that were chosen for further study." (PMID 36003411, 2022).
atherosclerosis (continued). "Increased accumulation of uremic toxins, oxidative stress, and inflammation, overactivation of the renin–angiotensin–aldosterone system systemically exacerbate atherosclerosis in this patient group." (PMID 35902808, 2022). "The enriched molecular signaling pathways of the core targets were involved in renin secretion, renin-angiotensin system, hypertrophic cardiomyopathy, fluid shear stress, and atherosclerosis adrenergic signaling in cardiomyocytes, in addition to others." (PMID 35498046, 2022). "Oxidized LDL (oxLDL) contributes to the development and progression of atherosclerosis through induction of inflammatory and immune cell infiltration into the vascular wall, increase of oxidative stress and upregulation of the renin–angiotensin system." (PMID 35456556, 2022). "In this review, firstly, we present the interplay between coagulation, inflammation, and the renin–angiotensin (RA) system and its altered role in atherosclerosis formation in premature CAD in women vs. men." (PMID 34356659, 2021). "Pathway enrichment analysis further suggested that these potential targets were mainly involved in the chemokine signaling, inflammation, atherosclerosis, and renin-angiotensin system." (PMID 34925046, 2021). "The renin-angiotensin system is essential for the pathogenesis of both coronavirus disease and atherosclerosis." (PMID 33946649, 2021). "Disturbances of the renin-angiotensin-aldosterone system are part of the physiopathology of atherosclerosis, supporting VSMC hypertrophy, proliferation and migration." (PMID 31921839, 2019). "It has been found that macrophage VDR signaling attenuates atherosclerosis in mice in part by inhibiting the local renin-angiotensin system." (PMID 30319417, 2018). "During hypoxic-atherosclerosis condition, the increase in renin concentration was higher than each conditions alone, which explains the synergistic effects of these two conditions." (PMID 28740628, 2017). "The present study was conducted to evaluate the effects of atherosclerosis and hypoxia on blood content of vasoconstrictors levels of epinephrine, norepinephrine and renin." (PMID 28740628, 2017). "Central to both atherosclerosis initiation and progression is the renin-angiotensin system, which plays a crucial role through several distinct mechanisms." (PMID 28646220, 2017). "AngII infusion accelerates atherosclerosis and blockade of the renin-angiotensin system is protective." (PMID 28646220, 2017). "The aim of present study was to evaluate the effects of atherosclerosis and hypoxia on serum levels of main vasoconstrictors (epinephrine, norepinephrine and renin)." (PMID 28740628, 2017). "They found a higher amount of MMP9 in comparison to their expression in atherosclerosis, which demonstrates their involvement in extracellular matrix degradation, smooth muscle cell apoptosis, renin-angiotensin system activity, and neovascularization." (PMID 29158612, 2017). "The role of systemic and local renin-angiotensin system in vascular remodeling diseases such as atherosclerosis and neointima hyperplasia after angioplasty is well established." (PMID 24804145, 2014). "Vitamin D has proven to be effective on renin expression, inflammatory response, oxidative stress, apoptosis, and atherosclerosis." (PMID 23843788, 2013). "The benefits of renin inhibition in atherosclerosis, especially when used in combination with angiotensin-converting enzyme inhibitors/angiotensin receptor blockers (ACEIs/ARBs) are currently not known." (PMID 23686372, 2013). "The renin–angiotensin system is well recognized as a mediator of pathophysiological events in atherosclerosis." (PMID 23686372, 2013). "Blood pressure is influenced by numerous factors including atherosclerosis, imbalances in the renin-angiotensin system, and hyperinsulinemia, the latter increasing sodium retention in the body and speeding up atherosclerosis." (PMID 22254045, 2010).
atherosclerosis (continued). "Enhanced expression of pro-inflammatory cytokines, renin and Ang II underlies the pathogenic mechanism of an active CMV infection to increase blood pressure and aggravate atherosclerosis." (PMID 19436702, 2009). "Onthe other hand, the renin-angiotensin system can modulate the activation ofcomplement system in both atherosclerosis and renal injury." (PMID 19390623, 2009). "Angiontenin II has been detected also in peripheral tissues (such as aortic tissue), suggesting a possible role of the local renin-angiotensin system in atherosclerosis." (PMID 19390623, 2009). "The crucial role of the renin-angiotensin system in inflammatory processes regulating atherosclerosis was also observed in other animal models prone to develop atherosclerosis." (PMID 19390623, 2009). "The inhibition of the renin-angiotensin system represents a pivotal approach for reducing atherosclerosis and its dramatic complications, such as stroke and myocardial infarction (MI)." (PMID 19390623, 2009). "The high prevalence in menopausal women may be related to sex hormones, renin-angiotensin-aldosterone, sympathetic nervous system and atherosclerosis." (PMID 40153757, 2025). "Exercise exerts beneficial effects on atherosclerosis through modulation of diverse pathways, including exerkines, browning of adipose tissue, the renin-angiotensin system (RAS), metabolites, gut microbiota, cell death pathways, microRNAs, nervous system, and immune function." (PMID 40861271, 2025). "Additionally, decreased renal function can influence the body's endocrine environment, such as through the activation of the renin-angiotensin system, which contributes to increased blood pressure and the progression of atherosclerosis." (PMID 41189989, 2025). "Adding the causal genes ACE, AGT, AGTR1, and REN to list 2+ (n = 9+4) revealed AOC3 with at least one causal gene to be associated with Transition Metal Ion Binding (GO:0046914, q = 2.288x10-2), and Atherosclerosis (q = 2.821x10-5)." (PMID 39480826, 2024). "Fluid shear stress and atherosclerosis, complement and coagulation cascade, rheumatoid arthritis, apoptosis, and renin secretion (Bauer, 1993)." (PMID 39157757, 2024). "Further studies on whether renal renin-angiotensin components affect atherosclerosis by deletion or increase of either renal AT1aR or AngII production in whole kidney will be considered when appropriate transgenic mice are available." (PMID 37655218, 2023). "Furthermore, aliskiren, a direct renin inhibitor, was shown to limit atherosclerosis and AAA in an Ang II-infused mouse model by reducing prorenin receptor expression and Mitogen-activated protein kinases activity." (PMID 37383707, 2023). "In addition to its established role in hypertension, the renin–angiotensin system (RAS) has major implications in atherosclerosis pathogenesis via various cellular and molecular mechanisms." (PMID 35456556, 2022). "The results of bioinformatics analysis revealed that urinary EV may participate in DN through various pathways such as angiogenesis, biogenesis of EV, renin-angiotensin system, fluid shear stress and atherosclerosis, collagen degradation, and immune system." (PMID 36034457, 2022). "In the present study, neither aldosterone nor renin was associated with markers of atherosclerosis in obese individuals." (PMID 32529242, 2020). "Several pieces of evidence converge to suggest that crosstalk between MDM2 and elements of the renin-angiotensin-aldosterone system could support atherosclerosis by modulating smooth muscle hypertrophy." (PMID 31921839, 2019). "Moreover, the enriched pathways analyzed by KEGG were MAPK signaling pathway, long-term potentiation, renin secretion, spliceosome, pentose phosphate, proteoglycans in cancer, fluid shear stress and atherosclerosis and steroid hormone biosynthesis." (PMID 31692917, 2019). "Interestingly, hydrochlorothiazide seems to neutralize the benefits of renin-angiotensin system blockade in the context of experimental atherosclerosis." (PMID 31721907, 2019).